FGF21 (fibroblast growth factor 21)
Diseases named in the same sentence as FGF21 in open-access papers (continued):
Sharing a sentence is not in itself a finding about the gene and the disease.
diabetes (continued). "They treated diabetic and control mice with FGF-21 for 10 days and showed, by TUNEL staining, that FGF-21 prevented diabetes-induced cardiac apoptosis and hypothesized a cardiac protective role of FGF-21 administration." (PMID 38667723, 2024). "Furthermore, the observation that FGF21 is upregulated in individuals with diabetes is widely acknowledged." (PMID 38789571, 2024). "The effect of FGF21 overexpression on osteoporosis may be mediated by type 2 diabetes mellitus and basal metabolic rate, with mediating effects of 14.96% and 12.21%, respectively." (PMID 39296716, 2024). "Additionally, this study is the first to observe the alleviation of diabetes-induced VSMC senescence by FGF21 and to investigate its potential mechanisms." (PMID 38733164, 2024). "In summary, FGF-21 exhibits remarkable biological efficacy in reducing blood glucose, alleviating inflammation, and ameliorating peripheral nerve injuries, promising to serve as a biomarker and therapeutic target for diabetes management." (PMID 38606083, 2024). "In addition, CTGF and FGF21 correlated positively with duration of diabetes (CTGF: r = 0.20, p = 0.02; FGF21: r = 0.31, p < 0.001)." (PMID 38540101, 2024). "In this paper, using two models of diabetes, we demonstrated that FGF21 ameliorates proteinuria, oxidative stress and inflammation, as well as fibrosis and glomerular podocyte loss or swelling, and impaired glomerular filtration barrier in mice with diabetic nephropathy." (PMID 39830349, 2024). "On the other hand, independent factors for STDR incidence were FGF21, age, diabetes duration, and diastolic blood pressure divided their samples into four quartiles with different levels of FGF21, with Q1 being the lowest (FGF21 < 388 pg/mL) and Q4 being the highest (FGF21 ≥ 580 pg/mL)." (PMID 39687000, 2024). "Our results also revealed that another five proteins (HGF, CD6, fibroblast growth factor 21 (FGF-21), LIF-R, and OSM) might mediate the associations of gut bacteria with diabetes." (PMID 38643166, 2024). "In addition, an increasing trend of FGF-21 in the normoglycemia group (146.6 [95.5, 247.3] pg/mL), prediabetes group (160.6 [104.3, 246.3] pg/mL), and diabetes group (257.8 [159.8, 339.2] pg/mL) was detected in this study (P for trend < 0.001)." (PMID 37658393, 2023). "Accordingly, we constructed the following two diabetes risk assessment models: Model 1 (including the noninvasive factors of sex, age, BMI, waistline, and SBP) and Model 2 (including sex, age, BMI, waistline, SBP, and FGF-21)." (PMID 37658393, 2023). "FGF21 levels were also significantly elevated in the dilated cardiomyopathy patients compared to controls who were well matched with age, sex, BMI, and history of diabetes even though the incidence of AF was greater in dilated cardiomyopathy patients." (PMID 36028609, 2023). "In the total population, the ORs of diabetes with increasing FGF-21 quartiles were 1.00, 1.24 (95% CI 0.56–2.80; quartile 2), 2.47 (95% CI 1.18–5.33; quartile 3), and 3.24 (95% CI 1.53–7.14; quartile 4) in Model 4 (P < 0.001), and the trend was consistent in different subpopulations." (PMID 37658393, 2023). "FGF-21 levels are typically reduced in patients with T2DM treated with anti-diabetes medications." (PMID 38035345, 2023). "Interestingly, the level of total FGF-21 in our patients with diabetes and MetS were lower than the one previously shown in literature." (PMID 37409233, 2023). "In addition, FGF21 ameliorates myocardial damage in diabetes by activating AMPK-AKT2-Nrf2-mediated antioxidant pathways and AMPK-ACC-CPT1-mediated lipid-lowering effects." (PMID 37576954, 2023). "The increase in FGF21 levels in diabetes may be due to metabolic disorders and decreased sensitivity to FGF21, so the compensatory synthesis and secretion of more FGF21 by the liver is needed to maintain the metabolic homeostasis of the body." (PMID 37576954, 2023).
diabetes (continued). "Univariate regression analysis indicated that a higher level of FGF-21 was significantly associated with higher odds of diabetes (P for FGF-21 < 0.001; P for nonlinear = 0.058)." (PMID 37658393, 2023). "Interestingly, we observed that chow-fed IRFKO mice have basal plasma FGF21 100 times higher than chow-fed WT mice, presumably due to the intrinsic severe lipodystrophy and diabetes in IRFKO mice." (PMID 37479751, 2023). "FGF21 has also been reported to have a protective effect against diabetes complications." (PMID 37576954, 2023). "At present, several studies have reported that FGF21 may be a biomarker for the occurrence of diabetes." (PMID 37576954, 2023). "Metabolic role of FGF21 let researchers to speculate that this protein can play an important role in a pathogenesis of gestational and type 2 diabetes mellitus, and it can also be a promising therapeutic target for metabolic disease." (PMID 37869250, 2023). "Further, in a streptozotocin-induced diabetic mouse model, FGF21 upregulated the ERK1/2 mitogen–activated protein kinase (p38 MAPK)/AMP-activated protein kinase (AMPK) pathway to protect against lipotoxicity-mediated cardiac apoptosis in diabetes." (PMID 36028609, 2023). "FGF21 levels can also be used to assess the effectiveness of diabetes treatment." (PMID 37576954, 2023). "FGF21 is involved in the pathological changes of diabetes, AS, and HP, respectively." (PMID 38057786, 2023). "Moreover, exogenous FGF21 intervention or overexpression of FGF21 can significantly slow the onset of diabetes." (PMID 37576954, 2023). "This study demonstrated that a high level of circulating FGF-21 was positively correlated with diabetes, and levels of FGF-21 could be an important biomarker for the assessment of diabetes risk." (PMID 37658393, 2023). "On the basis of results obtained from our study, it can be concluded that increased FGF21 concentration observed in diabetes may result from a compensatory reaction to impaired insulin sensitivity or tissue resistance to this cytokine." (PMID 37869250, 2023). "In the future, treatment with FGF21 in combination with drugs or exercise to improve FGF21 resistance may be a potential approach for the treatment of diabetes and its complications." (PMID 37576954, 2023). "FGF-21 was not significantly increased in high-risk conditions such as visceral obesity, Metabolic Syndrome, diabetes, smoking, and atherosclerosis." (PMID 37409233, 2023). "Because of their effects on liver and adipose tissue, especially FGF19 and FGF21 may be interesting with regard to the treatment of diabetes mellitus." (PMID 36699319, 2022). "In streptozotocin (STZ)-induced diabetes, cardiac FGF21 mRNA level is increased significantly." (PMID 35983184, 2022). "In the crude model with no adjustments, FGF21 levels were positively associated with the prevalence of CAD in men with diabetes, whereas serum total testosterone concentrations showed the opposite results contrary to FGF21." (PMID 35909513, 2022). "Increased plasma FGF21 levels might be attributed to the fact that HDAC3 inhibition can prevent diabetes-induced liver damage and enhance FGF21 expression and circulating secretion, including in diabetic conditions." (PMID 35656103, 2022). "Cell Metabolism (total link strength = 415,641 times), Diabetes, Journal of Biological Chemistry, Endocrinology, and Journal of the Clinical Investigation had the most co-citations with other journals, suggesting their important status in FGF-21 research." (PMID 36238554, 2022). "In addition, administration of FGF21 and its analog has beneficial effects on glycemic control in mice with both type 1 and 2 diabetes models and in humans with type 2 diabetes mellitus." (PMID 35192641, 2022).
diabetes (continued). "A mechanism study showed that the antiapoptotic effect induced by FGF21 in type 1 diabetes mellitus (T1DM) mice was attributed to the activation of AMPK, followed by the inactivation of phosphatase and tensin homolog (PTEN), which negatively regulates Akt signaling." (PMID 35069790, 2022). "Moreover, FGF21/adiponectin ratio independently predicted new-onset diabetes in subjects with prediabetes (OR 1.367 [95% CI 1.130–1.654], p = 0.001), no matter in males and females." (PMID 34321008, 2021). "FGF21/adiponectin ratio independently predicted new-onset diabetes in patients with prediabetes." (PMID 34321008, 2021). "Studies in human subjects have identified increased FGF-21 levels in cardiometabolic pathologies such as non-alcoholic fatty liver disease, coronary artery disease, diastolic heart failure, diabetes, and insulin resistance, mediating the adaptive response to various stresses." (PMID 33535425, 2021). "In this study, we provide further evidence that FGF21 is positively associated with subclinical atherosclerosis in women, but not in men, in a diabetes-enriched multiethnic cohort in Singapore." (PMID 33996935, 2021). "Similarly, serum FGF21 positively correlated with BMI, waist circumference, and adiposity in healthy men and those with diabetes in Tanzania." (PMID 35046901, 2021). "Two hours post-load plasma glucose and UACR were associated with FGF21 only in subjects without diabetes (n = 2065)." (PMID 34918690, 2021). "We aimed to study whether sex modulates the relationship between FGF21 and subclinical carotid atherosclerosis in a diabetes-enriched multiethnic population of Singapore." (PMID 33996935, 2021). "Therefore, we suggest that FGF21 ameliorates oxidative stress, which contributes to its protective effects against diabetes‐induced impairment of EPC mobilization." (PMID 33599110, 2021). "FGF21 also showed potential for treating cardiovascular complications of diabetes." (PMID 33599110, 2021). "Herein, the effect of FGF21 on glucose metabolism in LNCaP cells might be similar to that in previous reports of obese and type 2 diabetes mellitus populations and animals." (PMID 33753729, 2021). "Elevated baseline FGF21/adiponectin ratio was a significant predictor of new-onset diabetes independent of traditional risk factors, especially in subjects with prediabetes (odds ratio, 1.367; p = 0.001)." (PMID 34321008, 2021). "Leptin, adiponectin, GDF-15 and FGF-21 changes were related to weight loss not remission of diabetes." (PMID 33925808, 2021). "We further investigated whether FGF21/adiponectin ratio could be a clinically useful biomarker for diabetes prediction, using C statistics, NRI, and IDI." (PMID 34321008, 2021). "FGF21 is closely related to metabolic disorders including diabetes." (PMID 34675822, 2021). "When categorizing the MD patients according to their clinical phenotypes, we observed that FGF-21 levels were preferentially increased in patients with myopathy, exercise intolerance, and CPEO, and also discriminated patients with diabetes mellitus and hearing loss." (PMID 34203775, 2021). "Baseline FGF21/adiponectin ratio levels were predictive of new-onset diabetes in both age groups." (PMID 34321008, 2021). "However, the addition of FGF21/adiponectin ratio to Model 1 resulted in a significant improvement in predicting new-onset diabetes, with increments in NRI (27.1%, p < 0.001) and IDI (0.7%, p = 0.020)." (PMID 34321008, 2021). "BAT-secreted FGF21 prevents hyperglycemia and hyperlipidemia in mice, and FGF21 analogues tested in overweight/obese patients with type 2 diabetes mellitus have been shown to reduce dyslipidemia and hepatic steatosis, although they do not lead to improvements in glucose control and body weight." (PMID 33227979, 2020). "FGF21 regulates glucose and lipid metabolism and has potential for the treatment of diabetes." (PMID 32628815, 2020).
diabetes (continued). "By controlling Met levels, the conditions of glucose homeostasis, insulin sensitivity, and oxidative stress with activation of the fibroblast growth factor 21 and protein phosphatase 2A signals in diabetes may improve." (PMID 33319826, 2020). "However, pharmacological doses of FGF21 treatment have been shown to restore this impaired relationship even in human subjects with diabetes and NAFLD, as demonstrated in a small number of clinical trials." (PMID 33071964, 2020). "Further studies are needed to determine whether FGF21 resistance is involved in the pathogenesis of diabetes and atherosclerosis, and if there is a mechanism to overcome this resistance." (PMID 32227589, 2020). "Furthermore, FGF-21 supplementation prevented lipid- or diabetes-induced cardiac apoptosis and lipotoxicity-induced cardiomyopathy, possibly through inhibition of Fyn-mediated export of NRF-2 from the nucleus." (PMID 33317180, 2020). "Taken together, the data suggest that CaMKK2 may be an upstream regulator determining the activity of AMPKα and mediating the alleviating effects of FGF21 on diabetes-induced oxidative stress and endothelial dysfunction." (PMID 31511499, 2019). "Higher levels of FGF21 were expressed, particularly in patients with diabetes." (PMID 30959789, 2019). "However, circulating levels of FGF21 were significantly higher in PPGL with secondary diabetes mellitus and signs of metabolic syndrome." (PMID 30959789, 2019). "With a lower carbohydrate/fat ratio, NZO mice were protected from hyperglycaemia and beta cell loss, whereas under conditions of an increased carbohydrate/fat ratio, mice developed diabetes despite robustly elevated hepatic FGF21 secretion in response to dietary protein restriction." (PMID 29550873, 2018). "One recent study showed that FGF21 was associated with higher 10-year risk for coronary heart disease (CHD) in patients with no history of diabetes." (PMID 30185439, 2018). "We concluded that the diabetes-susceptible NZO mouse is not FGF21-resistant, and is a potential animal model to study dietary low-protein-triggered, FGF21-dependent outcomes related to diabetes prevention." (PMID 29550873, 2018). "Regardless of the presence of diabetes, the serum FGF21 concentration remained significantly associated with subsequent eGFR decline." (PMID 30127382, 2018). "Interestingly, FGF21 levels have been found to be increased in conditions such as obesity, MetS and diabetes in both animal studies and clinical reports." (PMID 29581470, 2018). "FGF21-KO mice were more sensitive to diabetes-induced cardiac dysfunction." (PMID 29445083, 2018). "However, in our study, the HOMA-IR level was lower in the high-FGF21 group, and the number of patients with diabetes was closely comparable between the high- and low-FGF21 groups." (PMID 28582462, 2017). "Higher serum FGF-21 level was associated with an increased risk of diabetes in Chinese women but not in men." (PMID 29021814, 2017). "Circulating FGF21 predicts cardiovascular events and mortality in type 2 diabetes mellitus, including early-stage chronic kidney disease, but its impact on clinical outcomes in end-stage renal disease (ESRD) patients remains unclear." (PMID 28582462, 2017). "A number of experimental evidence has shown that FGF-21 may involve in key etiological pathways leading to diabetes development such as regulation of lipid homeostasis, inflammation, and development of NAFLD." (PMID 29021814, 2017). "Later, an updated study in the same cohort focusing on diabetes prediction model reported that higher FGF-21 (≥178.2 versus <178.2 pg/mL) was associated with an increased diabetes risk independent of other blood biomarkers (OR, 1.60; 95% CI 1.18–2.16)." (PMID 29021814, 2017). "Furthermore, FGF21 can prevent isoproterenol-induced cardiac hypertrophy and diabetes-induced cardiac apoptosis through MAPK pathway in mice." (PMID 29109955, 2017).
diabetes (continued). "In addition, relationships between CTRP1 and other diabetes-related cytokines were elucidated, including adiponectin and fibroblast growth factor 21 (FGF21)." (PMID 27313611, 2016). "When serum levels of FGF19 were < 200 mg/mL and FGF21 > 500 mg/mL, 91% of patients had diabetes." (PMID 25664662, 2015). "This marks FGF21 as a potential therapy for the treatment of aortic damage due to diabetes." (PMID 27391008, 2015). "Prospective clinical trials using pharmacologic and/or nutritional interventions that can modulate circulating FGF19 and FGF21 levels could help elucidate further the exact roles of these two hormones in the pathophysiology of diabetes." (PMID 25664662, 2015). "FGF21 knockout mice with streptozotocin-induced diabetes exhibit severe cardiac dysfunction, increased cardiac lipid accumulation, and severe aortic remodeling, indicating that FGF21 plays roles in the development and progression of diabetic cardiomyopathy and aortic remodeling." (PMID 26483756, 2015). "The effect of FGF21 on the development and progression of diabetes-induced pathogenic changes in the aorta has not currently been addressed." (PMID 27391008, 2015). "It is of particular interest that it was either lower FGF19 or higher FGF21 serum levels that were signifciantly associated with diabetes or cardiometabolic phenotypes but never the two together." (PMID 25664662, 2015). "In response to endothelial dysfunction, serum adiponectin or FGF21, both as beneficial hormones to diabetes, may be compensatorily increased to repair microvascular legions involved in retinopathy." (PMID 24895642, 2014). "In addition, streptozotocin-induced diabetes in mice has been shown to suppress the stimulatory effect of starvation on hepatic FGF21 mRNA abundance." (PMID 24733293, 2014). "In addition, Oil Red O staining revealed that diabetes strongly increased lipid accumulation in the kidney, which was significantly attenuated by FGF21 treatment." (PMID 24349242, 2013). "Administration of FGF21 significantly prevented renal damage-induced diabetes." (PMID 24349242, 2013). "However, administration of FGF21 remarkably prevented diabetes-induced renal dysfunction and hypertrophy." (PMID 24349242, 2013). "Administration of FGF21 significantly prevented renal damage induced by diabetes." (PMID 24349242, 2013). "The pharmacological actions of FGF21 make it attractive as future drug for treating diabetes." (PMID 24260557, 2013). "However, administration of FGF21 almost completely suppressed the increased expression of all these inflammatory factors induced by diabetes in the kidney." (PMID 24349242, 2013). "In contrast, FGF21 significantly suppressed diabetes-induced elevations in renal TG levels." (PMID 24349242, 2013). "The present study investigated whether FGF21 can prevent hyperlipidemia- or diabetes-induced renal damage, and if so, the possible mechanism." (PMID 24349242, 2013). "Effect of FGF21 on diabetes-induced renal hypertrophy and dysfunction." (PMID 24349242, 2013). "Importantly, and for the first time we show that FGF21 based therapy has metabolic efficacy in an animal with late stage diabetes." (PMID 23823755, 2013). "Furthermore, in an animal with late stage diabetes, FGF21 therapy retained the majority of its efficacy with attenuation of only glycemic aspects of FGF21-mediated pharmacology." (PMID 23823755, 2013). "Thus, given the generally exceptional translational quality of the experimental data obtained in rhesus monkeys that developed diabetes in a natural way, we chose to evaluate our FGF21-based candidate, LY, in this model." (PMID 23823755, 2013). "Administration of FGF21 significantly protected renal cells from apoptosis induced by diabetes." (PMID 24349242, 2013).